TUG1 (taurine up-regulated 1)
Diseases named in the same sentence as TUG1 in open-access papers (continued):
Sharing a sentence is not in itself a finding about the gene and the disease.
Obesity (6 papers, 2020 to 2025). Accumulation of substantial excess body fat. "Recent studies point toward the possible regulatory roles of two lncRNAs; metastasis-associated lung adenocarcinoma transcript 1 (MALAT1) and taurine upregulated gene 1 (TUG1) in the pathogenesis of obesity-related disorders and regulation of lipogenesis and adipogenesis." (PMID 32368256, 2020). "Another noteworthy target is fat mass and obesity‐associated (FTO), identified within the SOX2‐OT/MIR222HG/HOXA‐AS3/TUG1, and SOX2‐OT/MIR222HG/HOXA‐AS3/TUG1/CASC2 subnetworks." (PMID 40066229, 2025). "Collectively, we observed a lower expression of TUG1 in obese women and its inverse correlation with obesity indices, hs-CRP, and creatinine levels." (PMID 32368256, 2020). "Although to the best of the authors’ knowledge, this study was one of the first to draw attention to the possible role of MALAT1 and TUG1 in the pathogenesis of obesity in humans, some limitations of the current study deserve to be mentioned." (PMID 32368256, 2020). "Despite our endeavors to understand the roles of lncRNAs MALAT1 and TUG1 in the context of metabolic disorders, the precise role of these lncRNAs in obesity and to understand how they interact with dietary factors remain unclear." (PMID 38167433, 2024). "However, VAT mRNA expression of TUG1 had a positive correlation with obesity indices and HOMA-IR and insulin levels in the whole population." (PMID 32368256, 2020). "Hence, it is tempting to speculate that the decreased expression of TUG1 in adipose tissue may be partly related to the inflammatory milieu in obesity which in turn exacerbates inflammation in obesity, reflected by high levels of hs-CRP." (PMID 32368256, 2020). "It seems likely that TUG1 with distinct expression pattern in VAT and SAT are involved in the regulation of lipogenic and adipogenic genes and obesity-related parameters." (PMID 32368256, 2020). "The exact mechanisms linking TUG1 and MALAT1 to the pathogenesis of obesity cannot be ascertained according to the present study." (PMID 32368256, 2020). "Consistent with our results, no notable correlation was observed between TUG1 and obesity-related parameters in VAT when accounting for age and HOMA-IR50." (PMID 38167433, 2024). "However, the transcription levels of MALAT1 and TUG1 showed a positive correlation with major lipogenic and adipogenic genes, and thus the authors suggested possible roles of MALAT1 and TUG1 in obesity." (PMID 38674413, 2024). "In an attempt to understand the molecules involved in human obesity pathogenesis, we aimed to evaluate the expression of MALAT1 and TUG1 in visceral adipose tissues (VAT) and subcutaneous adipose tissues (SAT) of obese women, as compared to normal-weight women." (PMID 32368256, 2020). "Therefore, in an attempt to realize the molecules involved in the pathogenesis of obesity, here, we aimed to evaluate the expression of MALAT1 and TUG1, as well as plausible target genes (PPARγ, PGC1α, SREBP-1c, FAS, and ACC), in VAT and SAT from obese women compared to normal-weight subjects." (PMID 32368256, 2020). "More importantly, MALAT1 and TUG1 transcript levels showed positive correlations with master lipogenic and adipogenic genes which might be indicative of the possible role of MALAT1 and TUG1 in obesity possibly through regulating the lipogenic and adipogenic genes." (PMID 32368256, 2020).
oral squamous cell carcinoma (6 papers, 2017 to 2023). "lncRNA TUG1 promoted cell growth, proliferation, and invasion, and induced apoptosis of oral squamous cell carcinoma cells by targeting the Wnt/β-catenin signalling pathway." (PMID 34039257, 2021). "TUG1 knockdown suppressed cell growth, proliferation, and invasion and also induced the apoptosis of oral squamous cell carcinoma by targeting Wnt/β-catenin signalling." (PMID 30595764, 2018).
Stroke (6 papers, 2021 to 2024). Sudden impairment of blood flow to a part of the brain due to occlusion or rupture of an artery to the brain. "This new understanding of the TUG1 mechanism not only advances our understanding of stroke pathophysiology but also offers new therapeutic possibilities to improve patient prognosis." (PMID 39595085, 2024). "An ROC curve was assembled to estimate the diagnostic value of TUG1, LINC00657, miR-9, and miR-106a as novel biomarkers for DM with stroke relative to healthy subjects." (PMID 35237654, 2021). "Recently, TUG1 has gained significant attention in ischemic injuries, although little has been identified regarding its role in DM complicated with stroke." (PMID 35237654, 2021). "Previous research has primarily focused on TUG1’s interaction with miRNAs, such as miR-204-5p and miR-145, through which it functions as a miRNA sponge to regulate the expression of genes involved in inflammation and apoptosis, adversely affecting recovery after stroke." (PMID 39595085, 2024). "The current study aimed to estimate the levels of four ncRNAs: TUG1 and its target miR-21, NBAT1, and miR-335 to determine their potential use as diagnostic and prognostic biomarkers in AIS patients and their possible relation to stroke-related risk factors and the patient’s thyroid profile." (PMID 36250025, 2022). "LncRNAs ANRIL (non-coding antisense RNA in the INK4 locus), MALAT1 (metastasis-associated lung adenocarcinoma transcript 1), MEG3 (maternally expressed 3), TUG1 (taurine upregulated 1) and ANRIL expression were significantly increased in stroke models." (PMID 35741740, 2022). "We next compared the expressions of TUG1, LINC00657, miR-9, and miR-106a in the sera of diabetic patients with stroke relative to healthy controls." (PMID 35237654, 2021). "Also, we revealed positive correlations between each of TUG1, LINC00657, and miR-9 and the National Institutes of Health Stroke Scale (NIHSS)." (PMID 35237654, 2021). "However, no previous reports have investigated the role of TUG1, LINC00657, miR-9, and miR-106a in stroke associated with DM." (PMID 35237654, 2021). "Furthermore, we revealed a marked elevation of the serum expressions of TUG1, LINC00657, and miR-9 in diabetic patients with stroke relative to those without stroke (p < 0.001 for TUG1 and LINC00657; p = 0.003 for miR-9)." (PMID 35237654, 2021). "The present research investigated the expression profiles of serum TUG1, LINC00657, miR-9, and miR-106a in diabetic patients with and without stroke." (PMID 35237654, 2021). "ROC curve analysis revealed that serum TUG1, LINC00657, miR-9, and miR-106a have good value as prognostic markers in discriminating diabetic patients with stroke from those without stroke." (PMID 35237654, 2021). "At the same time, we verified marked increases of serum TUG1, LINC00657, and miR-9 and a marked decrease of serum miR-106a in diabetic patients who had stroke relative to those without stroke." (PMID 35237654, 2021). "We observed low TUG1 and miR-106a and significantly high LINC00657 and miR-9 expression levels in the serum of diabetic patients without stroke compared to control participants." (PMID 35237654, 2021). "At the same time, we found marked increases of serum TUG1, LINC00657, and miR-9 and a marked decrease of serum miR-106a in diabetic patients who had stroke relative to those without stroke." (PMID 35237654, 2021). "Thus, in this article, we assessed the serum expression levels of TUG1, LINC00657, miR-9, and miR-106a in diabetic patients with and without stroke." (PMID 35237654, 2021). "In this study, we aimed to assess the serum expression levels of TUG1, LINC00657, miR-9, and miR-106a in diabetic patients who had stroke and those without cerebral stroke and to explore any association between these non-coding RNAs and clinico-laboratory data." (PMID 35237654, 2021).
Stroke (continued). "The results implied that serum TUG1, LINC00657, miR-9, and miR-106a could discriminate diabetic patients without stroke from healthy subjects." (PMID 35237654, 2021).
acute kidney injury (5 papers, 2020 to 2024). Sudden and sustained deterioration of the kidney function characterized by decreased glomerular filtration rate, increased serum creatinine or oliguria. "Researchers have demonstrated that lncRNA TUG1, when carried in exosomes derived from human urine-derived stem cells (USCs), plays a crucial role in inhibiting ferroptosis in the context of I/R-induced acute kidney injury (IRI-AKI)." (PMID 38385027, 2024).
Hyperglycemia (5 papers, 2020 to 2023). An increased concentration of glucose in the blood. "All the results demonstrated that TUG1 was down-regulated by hyperglycemia both in vitro and in vivo." (PMID 36794657, 2023). "Long noncoding RNA taurine-up-regulated gene 1 (TUG1) in kidneys may be down-regulated by hyperglycemia." (PMID 36794657, 2023). "Previous study suggests that expression of TUG1 may be regulated by hyperglycemia, and its downregulation could lead to the impairment of β-cell function in diabetic mice." (PMID 36794657, 2023). "TUG1 sponges miR-524-5p, which is downregulated in hyperglycemia." (PMID 35599572, 2022).
Hypertension (5 papers, 2019 to 2023). The presence of chronic increased pressure in the systemic arterial system. "LncRNA TUG1, AK098656, TRPV1, GAS5, and Inc-Ang362 are implicated in hypertension-related vascular remodeling, and H19, TUG1, and UCA1 are involved in AS." (PMID 36627571, 2023). "LncRNA TUG1 induces hypertension progression via mediating proliferative and migratory abilities in VSMCs." (PMID 35027983, 2022). "In 2018, Shi found that lncRNA TUG1/miR-145-5p/FGF10 regulated VSMC proliferation and migration of hypertension patients." (PMID 35635088, 2022). "Examples include AK098656, which promotes hypertension through regulation of vascular smooth muscle cells (VSMCs) functions, GAS5, which promotes vascular remodeling and is downregulated in hypertension, and the TUG1/miR-145-5p/FGF10 axis, which regulates proliferation and migration in VSMCs." (PMID 32392180, 2020).
male infertility (5 papers, 2021 to 2025). The inability of the male to effect fertilization of an ovum after a specified period of unprotected intercourse. "One of these mechanisms, or their combination, potentially underlies a 100% penetrant male infertility phenotype in TUG1 knock-out mouse models." (PMID 34083519, 2021). "Together, these results highlight the potential role of TUG1 in male infertility, warranting further investigation into its clinical utility." (PMID 40425698, 2025). "Depletion of lncRNA Tug1 locus resulted in abnormal spermatozoa number and morphology which induced male infertility." (PMID 37612724, 2023). "In vivo data showed that global Tug1 knockout had no phenotype except for male infertility caused by impaired spermatogenesis with defects in number of sperms and abnormal sperm morphology." (PMID 36173935, 2022).
Myocardial fibrosis (5 papers, 2021 to 2025). "LncRNA TUG1 involved myocardial fibrosis in DCM development through modulating miR‐145a‐5p/Cfl2 axis, and suppression of lncRNA TUG1 demonstrated improvement of cardiac function and fibrosis." (PMID 40831067, 2025). "The role of miR-133 in cardiac fibrosis, particularly miR-133b, is also modulated by lncRNAs; for instance, complementary patterns of TUG1 (taurine-upregulated gene 1) lncRNA, and miR-133b were identified in a rat model of myocardial fibrosis." (PMID 36975887, 2023). "Taurine upregulated gene 1 (TUG-1) is a long noncoding RNA that, besides myocardial fibrosis, potentiates hypertrophy, apoptosis, autophagy, and inflammation with a confirmed role in the development of HFpEF through several studies." (PMID 41465364, 2025). "In addition, the aberrant expression of TUG1 has been reported to promote cardiac FMT activation and contribute fibrosis under chronic hypoxia conditions, reflecting its crucial role in myocardial fibrosis." (PMID 34540908, 2021).
nasopharyngeal carcinoma (5 papers, 2020 to 2023). A carcinoma arising from the nasopharyngeal epithelium. "TUG1 knockdown inhibits nasopharyngeal cancer progression and epithelial–mesenchymal transition (EMT) by upregulating miR-384." (PMID 37190145, 2023). "Polydatin and solamargine downregulate taurine-upregulated 1 (TUG1), which shows high expression in nasopharyngeal cancer cells." (PMID 37190145, 2023). "lncRNA TUG1 promoted the progression of nasopharyngeal carcinoma by enabling miR-384 to inhibit the epithelial-mesenchymal transformation (EMT)." (PMID 34039257, 2021). "Promotion of miR-384 was indicated to inhibit cell growth and EMT by sponging lncRNA TUG1 in nasopharyngeal carcinoma." (PMID 33817254, 2020). "Moreover, TUG1 knockdown suppresses tumor growth of the nasopharyngeal cancer cell xenograft model by upregulating miR-384 and downregulating EMT progression." (PMID 37190145, 2023). "Therefore, polydatin and solamargine may inhibit the migration of nasopharyngeal cancer cells by regulating the TUG1–miR-384 axis." (PMID 37190145, 2023).
thyroid cancer (5 papers, 2020 to 2025). "Studies investigating the mechanism responsible for the aberrant expression of miR-145 in thyroid cancer demonstrated the role of three ncRNAs (TUG1, n384546, and circNUP214) in suppressing miR-145 expression." (PMID 36077665, 2022). "TUG1 has been shown to enhance cell proliferation, migration, and epithelial–mesenchymal transition (EMT) in thyroid cancer cells." (PMID 41150811, 2025). "Mechanistically, TUG1 appears to exert its effects through the miR-145/ZEB1 signaling pathway, highlighting its potential relevance in the prognosis and therapeutic targeting of thyroid cancer." (PMID 41150811, 2025). "The deregulated ceRNA network of the TUG1/miR-145/zinc finger E-box binding homeobox 1 (ZEB1) signaling pathway increased cell proliferation, enhanced migration capacity, and promoted EMT formation in three thyroid cancer cell lines (the ATC cell lines SW1736 and KAT18 and the FTC cell line FTC133)." (PMID 36077665, 2022).
COVID-19 (4 papers, 2022 to 2024). A disease caused by infection with severe acute respiratory syndrome coronavirus 2. "The lncRNAs NEAT1, MALAT1, and Tug1 are lncRNA-related therapeutic targets for the treatment of COVID-19 patients." (PMID 36204652, 2022). "IL-6 had the highest accuracy in distinguishing COVID-19 patients (AUC=1, P<0.001 at a cutoff of 0.359), followed by TUG1 (AUC=0.999, P<0.001 at a cutoff of 2.28)." (PMID 35982898, 2022). "With respect to the TUG1 expression, it was substantially elevated in both severe and moderate COVID-19 patients, more than a thousand-fold higher than the controls." (PMID 35982898, 2022). "According to previous studies, lncRNA MALAT1, lncRNA NEAT1, and lncRNA TUG1 were upregulated in COVID-19." (PMID 36204652, 2022). "Previous studies have shown that lncRNA MALAT1 can regulate IL-6 and NLRP3 inflammatory cytokines, and lncRNA TUG1 plays an important role in the anti-inflammatory response to COVID-19 by blocking IL-6 cytokines." (PMID 36204652, 2022). "Furthermore, TUG1 expression was remarkably high in the moderate COVID-19 group compared to controls (P<0.001)." (PMID 35982898, 2022). "This striking overexpression of NEAT1 and TUG1 in severe and moderate COVID-19 patients may explain the prominent role of lncRNAs in COVID-19 and may augment their use as targets for control and downregulation in the management of COVID-19 infection." (PMID 35982898, 2022). "Therefore, the current study aimed to investigate lncRNAs, particularly NEAT1 and TUG1, and their association with IL-6, CCL2, and TNF-α in COVID-19 patients with moderate and severe disease." (PMID 35982898, 2022). "Importantly, the role of PTEN gene in the ceRNA network predicted by lncRNA MALAT1 and lncRNA TUG1 may help in the discovery and clinical treatment of effective drugs for COVID-19." (PMID 36204652, 2022). "predicted lncRNA MALAT1 - hsa-miR-92b-3p/hsa-miR-106b-3p/hsa-miR-25-3p - PTEN and lncRNA TUG1 - hsa-miR-29a-3p/hsa-miR-29b-3p/hsa-miR-144-3p - PTEN networks may provide new targets for COVID-19 treatment and drug development, but the specific mechanism of action requires further study." (PMID 36204652, 2022). "Four lncRNAs, MALAT1, NEAT1, TUG1 and GAS5 are predicted as potential therapeutic targets in COVID-19." (PMID 36204652, 2022). "PTEN is also upregulated in the ceRNA network predicted by lncRNA TUG1; thus, the lncRNA TUG1-hsa-miR-29a-3p/hsa-miR-29b-3p/hsa-miR-144-3p-PTEN network has the potential to play a role in the COVID-19 anti-inflammatory response and ARDS." (PMID 36204652, 2022). "In the severe COVID-19 group, we observed that NEAT1 expression was negatively correlated with TLC and positively correlated with TUG1 and CCL2 expressions." (PMID 35982898, 2022). "In the moderate COVID-19 group, NEAT1 was negatively correlated with oxygen but positively with age, TUG1 expression, CCL2, TNF-α, and IL-6 expression." (PMID 35982898, 2022). "COVID-19 and NAFLD progression may regulate ferroptosis through the CYBB-hsa-miR-196a/b-5p-TUG1 axis." (PMID 37335656, 2023). "Furthermore, TUG1 had a positive correlation with CCL2 and TNF-α, implying that TUG1 is involved in CCL2 and TNF-α production, which explains its role in COVID-19." (PMID 35982898, 2022). "Finally, we predict the possible therapeutic targets of four lncRNAs, MALAT1, NEAT1, TUG1, and GAS5, in COVID-19." (PMID 36204652, 2022). "NEAT1 and TUG1 had significant correlations with the measured cytokines, and based on the multivariate regression analysis, NEAT1 is the independent predictor for survival in COVID-19 patients (P=0.02)." (PMID 35982898, 2022). "Therefore, we hypothesized that the ferroptosis during the progression of COVID-19 and NAFLD might be regulated through the CYBB-hsa-miR-196a/b-5p-TUG1 axis." (PMID 37335656, 2023).
COVID-19 (continued). "Regarding TUG1 expression, it was significantly higher in the severe COVID-19 group than in the controls (P<0.001), with a thousand-fold difference, whereas the difference between the severe and moderate COVID-19 groups was not significant (P=0.92)." (PMID 35982898, 2022).
idiopathic pulmonary fibrosis (4 papers, 2023 to 2025). Idiopathic pulmonary fibrosis (IPF) is a nonneoplastic pulmonary disease that is characterized by the formation of scar tissue within the lungs in the absence of any known cause. "TUG1 is also a regulator of lung fibrosis caused by hypoxia, and an important regulator of cardiac fibroblast-myofibroblast transformation." (PMID 36794657, 2023). "Further, LncRNA TUG1 promotes the idiopathic pulmonary fibrosis progression of interstitial lung disease via activating the PI3K/Akt/mTOR pathway." (PMID 38582846, 2024). "Lnc-TUG1 promotes pulmonary fibrosis progression via up-regulating CDC27 and activating PI3K/Akt/mTOR pathway." (PMID 39133718, 2024).
intrahepatic cholangiocarcinoma (4 papers, 2017 to 2021). A carcinoma that arises from the intrahepatic bile duct epithelium in any site of the intrahepatic biliary tree. "LncRNA TUG1 has been reported to promote glutamine metabolism by inhibiting miR-145 in intrahepatic cholangiocarcinoma (ICC)." (PMID 33849550, 2021). "It has been shown that lncRNA taurine upregulated gene 1 (TUG1) expression is augmented in intrahepatic cholangiocarcinoma (ICC) samples, correlating with poor prognosis and adverse clinical pathological outcomes." (PMID 32326003, 2020). "In this study, we investigated the role of TUG1 in the pathogenesis of intrahepatic cholangiocarcinoma (ICC)." (PMID 29371936, 2017).